FOXO3 (forkhead box O3)
Diseases named in the same sentence as FOXO3 in open-access papers (continued):
Sharing a sentence is not in itself a finding about the gene and the disease.
renal carcinoma (10 papers, 2015 to 2025). A carcinoma arising from the epithelium of the renal parenchyma or the renal pelvis. "The molecular network confirmed by IPA also showed the key involvement of miR-181a and its association with renal cancer and dysfunction directly or indirectly via JNK1, FOXO1, FOXO3, and PDCD4." (PMID 41462911, 2025). "LncRNA URRCC facilitates proliferation and metastasis of renal cancer by regulating the EGFL7/P-AKT/FOXO3 signaling pathway and indicates poor survival in patients." (PMID 34322379, 2021). "To evaluate the role of FOXO3 in BCA-mediated apoptosis in renal cancer cells, we silenced the FOXO3 expression in A498 and ACHN cells and revealed the protein expression levels of PARP and FOXO3 using western blot assay." (PMID 34745413, 2021). "Collectively, our study findings revealed that the apoptotic effects of BCA against human renal cancer cells occur via the elevation of ROS level and activation of the FOXO3 signaling pathway." (PMID 34745413, 2021). "We elucidated the apoptotic activities of BCA, including the inhibition of cell proliferation and colony formation, G2/M cell cycle arrest, cellular apoptosis, ROS-mediated DNA damage, and translocation of FOXO3 protein into the nucleus in renal cancer cells." (PMID 34745413, 2021). "However, contrary to our findings, others observed that reduced expression of miR-182-5p was associated with disease development, including DKD41 and human renal carcinoma cells (RCC) via activation of AKT/FOXO3 signalling pathway." (PMID 35260775, 2022). "Therefore, our results suggest that BCA can trigger the translocation of the FOXO3 protein from the cytoplasm to the nucleus in renal cancer cells." (PMID 34745413, 2021). "Taken together, our results suggest that BCA treatment may induce FOXO3-mediated apoptosis in human renal cancer cells." (PMID 34745413, 2021). "Notably, Foxo3 was shown to upregulate miR-30d in renal carcinoma, thereby inducing cell cycle arrest and apoptosis." (PMID 26195352, 2015). "Altogether, our data suggested that URRCC could enhance renal cancer cell proliferation and invasion through EGFL7/P-AKT/FOXO3 signaling." (PMID 30953521, 2019).
Autoimmunity (9 papers, 2013 to 2025). The occurrence of an immune reaction against the organism's own cells or tissues. "The mild signs of disturbed tolerance in aged Foxo3cKO mice led us to determine the role of Foxo3 in the context of a genetically susceptible model for autoimmunity." (PMID 38773063, 2024). "Loss of FOXO1 and FOXO3 in T cells results in uncontrolled T cell activation and autoimmunity, which is at least in part linked to defects in the generation of regulatory T cells." (PMID 23378844, 2013). "Foxo3 is associated with regulatory DC and its deficiency may cause excessive T-cell proliferation and autoimmunity." (PMID 40022134, 2025). "Unlike the seemingly opposing effects on T cell survival, FOXO1 and FOXO3 co-operatively protect against autoimmunity." (PMID 23378844, 2013). "The autoimmunity in STK4 deficiency may also be due to the defective regulation of development and function of regulatory T cells through modulation of FOXO1/FOXO3." (PMID 39339890, 2024). "Indeed, FOXO3 KO mice suffer autoimmunity due to defective Treg development." (PMID 36991169, 2023). "In addition to Foxo1, Foxo3 is also expressed in immune cells and Foxo3−/− mice do not develop spontaneous autoimmunity or purified T cells have no defect in proliferation or survival." (PMID 29867972, 2018).
Cachexia (9 papers, 2011 to 2023). Severe weight loss, wasting of muscle, loss of appetite, and general debility related to a chronic disease. "MAFbx/atrogin-1 and MuRF-1 are key E3 Ub-ligases accounting for the muscle protein degradation under cachexia conditions, and FoxO3 is primarily responsible for the induction of MAFbx/atrogin-1 and MuRF-1." (PMID 27323407, 2016). "During the initiation of cachexia, Foxo3 phosphorylation was reduced by 39% (P = 0.001), and further reduced during the transition to intermediate weight loss, but not further reduced with extreme body weight loss." (PMID 21949739, 2011). "It appears plausible that a similar FOXO3‐dependent mechanism occurs in adipocytes, especially since visceral adipocytes showed several transcriptomic and macroscopic changes reminiscent of a “cachexia‐like” phenotype." (PMID 36795015, 2023). "Interestingly, many of the cachexia associated genes such as FOXO1, FOXO3, SIRT1, SMAD3 and FABP3 were identified in age related gene expression in similar direction." (PMID 33923976, 2021). "A total of 340 genes from muscle, including several known genes for cachexia such as FOXO1, FOXO3, PIK3RI, GLUL were correlated with CWLG." (PMID 33923976, 2021). "We found genes commonly identified in animal models of cachexia, such as FOXO1, FOXO3, IL6R, ZIP14 and PIK3R1, manifested in two independent muscle human datasets." (PMID 33923976, 2021). "At the onset of cancer cachexia, direct BRD4 and BRD2 recruitment at muscle catabolic genes is likely favored by local increase in histone acetylation, in concert with sustained engagement of transcription factors (e.g., FoxO3) and co-factors at chromatin regulatory regions." (PMID 29167426, 2017).
chronic kidney disease (9 papers, 2017 to 2025). Impairment of the renal function secondary to chronic kidney damage persisting for three or more months. "Vascular aging increases the risk of developing chronic kidney disease, and FOXO3 inactivation is involved in the development of aging-related vascular disease." (PMID 37553608, 2023). "Ellagic acid (EA) exerts reno-protective effects through miR-182/FOXO3 to improve chronic renal failure, and curcumin and resveratrol inhibit contrast-induced renal inflammation through the miR-30 / FOXO3 signaling pathway." (PMID 37553608, 2023). "The deletion of FoxO3 in renal tubular cells during the transition from acute kidney injury to chronic kidney disease decreases autophagy and exacerbates oxidative damage to the kidney, leading to severe fibrosis." (PMID 37553608, 2023). "PGC‐1 has also been shown to protect skeletal muscle wasting by suppressing the action of FoxO3 and the expression of atrogin‐1 and MuRF‐1 in rats with chronic renal failure." (PMID 32845566, 2020). "The FOXO3 protein might play a protective role in chronic kidney disease by preventing mitochondrial damage and ameliorating fibrosis." (PMID 36143124, 2022). "Therefore, it can be inferred that the molecular processes responsible for the development of left ventricular hypertrophy (LVH) in chronic kidney disease (CKD) are not influenced by FOXO3, ERK1/2, AMPK, and AKT/mTOR-mediated pathways." (PMID 38074330, 2023). "It is worth noting that the ratio of phosphorylated-AKT to total AKT was found to be elevated in individuals with chronic kidney disease (CKD), with no significant impact on the phosphorylation of FOXO3 or mTOR." (PMID 38074330, 2023).
clear cell renal cell carcinoma (9 papers, 2015 to 2025). "In clear cell renal cell carcinoma, low levels of FOXO3 mRNA were observed to be an independent prognostic factor for metastases based on a multivariate Cox regression analysis." (PMID 38202222, 2023). "Previously we reported that IL4Rα and IL13Rα1 (Type II receptor) is a prognostic marker and involved in the development of clear cell renal cell carcinoma (ccRCC) through JAK2/FOXO3 pathway." (PMID 35207737, 2022). "In addition, FOXO3 has been linked to tumor metastasis, given its inactivation induces Snail expression and enhances tumor cell EMT, thereby facilitating invasion and metastasis, as observed in renal clear cell carcinoma." (PMID 40589632, 2025).
systemic lupus erythematosus (9 papers, 2010 to 2024). An autoimmune multi-organ disease typically associated with vasculopathy and autoantibody production. "In parallel, a significant increase in the p-FOXO3/FOXO3 ratio was observed in lupus mice compared to sham mice and this increase was significantly reversed in cinnamon-treated mice (CL and CLC)." (PMID 39061948, 2024). "In our study, the p-FOXO3/FOXO3 ratio increased in the brain tissue of lupus mice, while cinnamon administration significantly attenuated the effect of TLR7 induction on the phosphorylation of FOXO3." (PMID 39061948, 2024). "The suppression of disease phenotype in lupus mice models was possible by the inhibitory peptide that acted via FoxO3 while FoxO1 level correlated with disease severity in several lupus patients." (PMID 34102081, 2021). "FoxO3 plays an important role in improving symptoms of glucocorticoid-mediated systemic lupus erythematosus (SLE) by inhibiting NF-κB activity." (PMID 36233176, 2022). "Array and western blot analyses showed non-significant increases in the p-NRF2/NRF2 and p-FOXO3/FOXO3 ratios in cell cultures treated with the plasma of lupus mice." (PMID 39061948, 2024). "Besides FOS, FOXO1, and FOXO3, upregulated TBK1 and TNFSF10 contributed to the activation prediction of ‘Systemic Lupus Erythematosus In B Cell Signaling’." (PMID 35406685, 2022). "SMAD2, GATA3, and FOXO3 could also be the miR-200a-3p targets in SLE and our lupus-like models." (PMID 29349090, 2017). "In accordance with a previous study in lupus-prone (BXSB, MRL/lpr) mice, we also observed decreased expression of FOXO3, a transcription factor that participates in negative regulation of Th1 responses." (PMID 20976278, 2010).
metabolic syndrome (8 papers, 2014 to 2024). A cluster of metabolic risk factors for CARDIOVASCULAR DISEASES and TYPE 2 DIABETES MELLITUS. "Interestingly, protective variants near FOXO3 are associated with a reduction in metabolic syndrome, but also with a reduction in cognitive ability." (PMID 32678081, 2020). "This study also showed that DHA supplementation restrained expression of FoxO1 and FoxO3 in pig adipocytes and human kidney HEK293T cells, suggesting that FoxO are potential therapeutic targets for DHA in ameliorating metabolic syndromes." (PMID 34371822, 2021). "Furthermore, there was a gene–gene interaction between FOXO3 rs2802292 and FABP1 rs2241883 regarding the diagnosis of dyslipidemia by K/DOQI (TBA 0.59, p-value 0.021)." (PMID 36143124, 2022).
multiple myeloma (8 papers, 2015 to 2026). "In addition, similar to GSDME, FOXO3 is also downregulated in MM and its restoration suppresses myeloma tumor growth." (PMID 41694578, 2026). "IGF-1 treatment of multiple myeloma cells led to reduced histone H3 tail Lys9 (H3K9) acetylation, and increased H3K9 dimethylation, which contributed to the silencing of the bim and foxO3 genes." (PMID 26405162, 2015). "IGF-1 suppresses Bim expression in multiple myeloma through several mechanisms including activation of the Akt pathway, inactivation of FoxO3, promotion of ERK-induced proteasomal degradation of BimEL and epigenetic regulation of the bim and foxO3a promoters." (PMID 26405162, 2015).
polycystic ovary syndrome (8 papers, 2020 to 2025). A disorder that manifests as multiple cysts on the ovaries. "Moreover, altered Foxo3 expression was associated with apoptosis in the GCs of women with polycystic ovary syndrome." (PMID 34201585, 2021). "Moreover, in patients with polycystic ovary syndrome (PCOS), researchers found a strong positive correlation between GC apoptosis and total FoxO3 levels; however, a negative relationship was observed with the phosphorylated FOXO3 protein (p-FOXO3) levels." (PMID 40428322, 2025). "YTHDF2 upregulates FOXO3 mRNA in GCs and contributes to the progression of non-obese polycystic ovary syndrome (PCOS) in women." (PMID 38397033, 2024). "Therefore, we hypothesize that LNK negatively regulates insulin-activated AKT/FOXO3 pathway and promotes granulosa cell apoptosis and dysfunction, therefore affecting oocyte maturation and thus participates in the etiology of ovulation disorder in polycystic ovary syndrome." (PMID 33495419, 2021).
chronic obstructive pulmonary disease (7 papers, 2015 to 2025). A chronic and progressive lung disorder characterized by the loss of elasticity of the bronchial tree and the air sacs, destruction of the air sacs wall, thickening of the bronchial wall, and mucous accumulation in the bronchial tree. "Both catalase and MnSOD are under the control of Forkhead box class O 3a (FoxO3), which significantly decreased in lungs of smokers and patients with chronic obstructive pulmonary disease, as well as in lungs of mice exposed to CS." (PMID 28105251, 2016). "Moreover, studies have shown that FoxO3−/− mice displayed signs of premature aging of the enteric nervous system, and FOXO3Adownregulation was also reported in other inflammatory diseases, such as ankylosing spondylitis, chronic obstructive pulmonary disease (COPD), and ulcerative colitis (UC)." (PMID 40034697, 2025).
depression (7 papers, 2016 to 2024). "Evidently, IPA unearthed a substantial number of genes, like Disc169, Syn370, Synpo71, Grin2a, Gria1, Foxo3, and many others which reportedly have been shown to be linked with depressive disorder, bipolar disorder and/or SSDs." (PMID 34362910, 2021).
injury (7 papers, 2019 to 2025). Damage inflicted on the body as the direct or indirect result of an external force, with or without disruption of structural continuity. "It is possible that increased expression of miR-132-3p can inhibit the expression of FOXO3, thereby suppressing the NF-κB pathway activated by FOXO3, weakening the LPS-induced inflammatory response and apoptosis, thereby reducing inflammation caused by acute lung injury." (PMID 37261284, 2023). "Icariin-induced protective effects against intestinal I/R-induced acute lung injury are mediated through the SIRT1/FOXO3 signaling pathway." (PMID 34630849, 2021).
Myocardial fibrosis (7 papers, 2021 to 2025). "Quercetin regulated miR-223-3p/FOXO3 to promote autophagy and prevent isoproterenol-induced myocardial fibrosis." (PMID 41178953, 2025). "Quercetin was also found to regulate miR-223-3p/FOXO3 axis to promote autophagy and suppress isoproterenol-induced myocardial fibrosis." (PMID 41178953, 2025). "Quercetin can inhibit myocardial fibrosis and improve atrial fibrillation by regulating the expression of miR-223-3p/ Fork head Box Protein O3 (FOXO3) and activating autophagy." (PMID 38054093, 2023). "Inhibiting the expression of miR-223-3p in AF model cells and rat myocardial tissue, enhancing the expression of FOXO3, activating autophagy pathway, inhibiting myocardial fibrosis." (PMID 37608811, 2023). "Novel evidence has suggested that the inhibition of miR-223-3p expression could upregulate the expression of FOXO3 and activate the autophagy pathway, thereby significantly inhibiting myocardial fibrosis and improving myocardial remodeling in AF." (PMID 34698362, 2021).
oral cancer (7 papers, 2017 to 2024). "CDDP induced colon, lung, and oral cancer cell death through FOXO3 mediation." (PMID 29299162, 2017).
type 1 diabetes (7 papers, 2016 to 2025). "Consistent with this, the blue module includes known type 1 diabetes–associated genes such as FOXP3 and FOXO3." (PMID 41306972, 2025).
COVID-19 (6 papers, 2021 to 2024). A disease caused by infection with severe acute respiratory syndrome coronavirus 2. "Treatment with compound PI-7 increased FOXO3 protein levels, reduced NF-κB, and diminished the levels of inflammatory cytokines belonging to the cytokine storm in COVID-19 patients." (PMID 38816514, 2024). "The identified TFs, such as FOXC1, GATA2, YY1, FOXL1, FOXO3, STAT1 and STAT3, are associated with COVID-19." (PMID 37261353, 2023). "We not only confirmed proteins identified in previous studies, such as SFTPD which affects COVID-19 and FOXO3 which affects healthspan, notably we identified several proteins with functions involved in inflammation and immune function, apoptosis, metabolism and hormone regulation." (PMID 38575325, 2024). "Among these, the expression levels of FOXK2, FOXO3, and FOXP1 were found lower in the lungs of COVID-19 patients, compared to controls, thus showing the same expression levels and trends as observed for ATP2B1 (Fig. EV1G,H)." (PMID 38816514, 2024). "Since FOXO3 shows the same expression trend as ATP2B1, with reduced expression levels in the lung of COVID-19 patients (ATP2B1, Fig. EV1G; FOXO3, Fig. EV3E) we hypothesized that FOXO3 is a candidate transcription factor that would be able to control ATP2B1 expression." (PMID 38816514, 2024).
endothelial dysfunction (6 papers, 2014 to 2025). In vascular diseases, endothelial dysfunction is a systemic pathological state of the endothelium (the inner lining of blood vessels) and can be broadly defined as an imbalance between vasodilating and vasoconstricting substances produced by (or acting on) the endothelium. "The presence of noise-induced O2•− in the tissue may deplete vasodilatory •NO, resulting in a neuroinflammatory phenotype and loss of the protective antioxidant transcription factor Foxo3, exacerbating the oxidative imbalance and potentiating endothelial dysfunction in the brain." (PMID 38142584, 2024). "Pharmacological activation of FoxO3 using bepridil successfully countered noise-induced oxidative stress in the aorta and the resulting endothelial dysfunction." (PMID 38142584, 2024). "Impaired FOXO3 signaling is likely a key mechanism in animal models with low-level noise exposure since the activation of FOXO3 by the calcium antagonist bepridil significantly improved several vital parameters, such as endothelial dysfunction and vascular/cerebral oxidative stress." (PMID 38142584, 2024).
head and neck squamous cell carcinoma (6 papers, 2018 to 2025). A squamous cell carcinoma that arises from any of the following anatomic sites: lip and oral cavity, nasal cavity, paranasal sinuses, pharynx, larynx, and salivary glands. "A more recent study shows that inhibition of DYRK1A decreased phosphorylation of FOXO3 on Ser253 by downregulation of AKT activity in head and neck squamous cell carcinoma cell lines." (PMID 33316942, 2020).
hemangioma (6 papers, 2015 to 2023). A benign vascular lesion characterized by the formation of capillary-sized or cavernous vascular channels. "We and others previously showed that mice somatically depleted of FOXO1 along with its 2 close paralogs, FOXO3 and FOXO4, are predisposed to the development of thymic lymphomas and hemangiomas." (PMID 36282572, 2022).